CFL1 (cofilin 1)
Diseases named in the same sentence as CFL1 in open-access papers (continued):
Sharing a sentence is not in itself a finding about the gene and the disease.
Infertility (4 papers, 2014 to 2025). "For PADI6 mutations inducing early infertility, this affects the expression of certain genes essential for cytokinesis during the early stages of embryogenesis, such as that of cofilin-1 (CFL1), which is involved in the organization of the actin cytoskeleton." (PMID 33228136, 2020). "The expression of CFL1 is associated with a history of infertility." (PMID 39872538, 2024). "De-regulation of the expression of Sorcin, Cofilin-1, Apo-A1 and Ran, during early- to mid-secretory phase may have physiological significance and it may be one of the causes for altered differentiation and/or maturation of endometrium, in women with unexplained infertility." (PMID 25405865, 2014). "Sorcin, Cofilin-1, Apo-A1 and Ran were performed in separate endometrial biopsy samples from infertile women." (PMID 25405865, 2014). "Silencing CFL1 significantly reduced PDGF’s proliferative effect, supporting the hypothesis of CFL1’s role in endometriosis-related infertility." (PMID 40072086, 2025). "In case of Cofilin-1, up-regulated expression was observed in stroma (2.4 fold), LE (1.9 fold) and GE (2 fold) of mid-secretory phase (LH+7) as compared to early-secretory phase (LH+2) endometrium of infertile women." (PMID 25405865, 2014). "The increased expression of Cofilin-1 in receptive phase endometrium of infertile women might be because of improper actin polymerization and depolymerization." (PMID 25405865, 2014).
lung adenocarcinoma (4 papers, 2011 to 2021). A carcinoma that arises from the lung and is characterized by the presence of malignant glandular epithelial cells. "Pathological analysis showed that PKM2 and cofilin-1 are promising diagnostic and prognostic biomarkers for lung adenocarcinoma." (PMID 22087286, 2011). "In the present study, cofilin-1 was found to be overexpessed in lung adenocarcinoma and overexpression of cofilin-1 was correlated with a low degree of differentiation." (PMID 22087286, 2011). "The data presented in this study suggested that both PKM2 and cofilin-1 could be developed as valuable prognostic factors, as well as potential therapeutic targets for lung adenocarcinoma." (PMID 22087286, 2011). "Cofilin-1 immunostaining results of patients with lung adenocarcinoma." (PMID 22087286, 2011). "Multivariate analyses using Cox proportional hazard model showed that both PKM2 and cofilin-1 could be developed as an independent prognostic factor for lung adenocarcinoma." (PMID 22087286, 2011). "The 5-year overall survival rate for the PKM2-/cofilin-1- strongly positive group was very poor (0%), compared with the other two groups, suggesting combination of the two markers may facilitate a more accurate prognosis of lung adenocarcinoma." (PMID 22087286, 2011). "Furthermore, Kaplan-Meier survival analysis showed that cofilin-1 could serve as an independent prognostic factor for lung adenocarcinoma." (PMID 22087286, 2011).
non-small cell lung carcinoma (4 papers, 2015 to 2021). A group of at least three distinct histological types of lung cancer, including non-small cell squamous cell carcinoma, adenocarcinoma, and large cell carcinoma. "Mechanistic study showed that suppression of cancer cell growth and invasion due to over-expression of CFL1 might be associated with up-regulation of let-7 microRNA in human non-small cell lung cancer (NSCLC) cells." (PMID 33791303, 2021). "For example, the overexpression of Cfl-1 suppressed growth and invasion of non-small cell lung cancer, and the phosphorylation of cofilin was elevated in bladder cancer samples compared with the normal bladder tissues." (PMID 28025492, 2016).
Alzheimer disease (3 papers, 2020 to 2023). A progressive, neurodegenerative disease characterized by loss of function and death of nerve cells in several areas of the brain leading to loss of cognitive function such as memory and language. "Previously, CFL1 has been implicated in the development of neurodegenerative diseases (Alzheimer’s disease and Huntington’s disease), neuronal migration disorders (lissencephaly, epilepsy, and schizophrenia), neural tube closure defects and memory consolidation during sleep." (PMID 37841864, 2023).
Anxiety (3 papers, 2012 to 2017). Intense feelings of nervousness, tension, or panic often arise in response to interpersonal stresses. "Cofilin-1 is a mouse anxiety gene with a knockout having a concordant outcome to the fly WAFO result." (PMID 27020741, 2016). "Cfl1 is likely to affect anxiety via the hippocampus, and more specifically the ventral hippocampus." (PMID 23055942, 2012). "We confirmed experimentally that forebrain-specific inactivation of Cfl1 decreased anxiety in knockout mice." (PMID 23055942, 2012). "By searching for common Gene Ontology functions in candidate genes positioned within those intervals, we identified actin depolymerizing factors (ADFs), including cofilin-1 (Cfl1), as genes involved in regulating anxiety in mice." (PMID 23055942, 2012). "Unexpectedly, annotations implicate actin depolymerizing factors (ADFs), including cofilin-1 (Cfl1), as being involved with the expression of anxiety phenotypes in mice." (PMID 23055942, 2012). "We confirmed that forebrain-specific inactivation of Cfl1 decreased anxiety in knockout mice." (PMID 23055942, 2012). "Fine-mapping of anxiety-related traits in the Northport HS together with analysis of functional gene annotations and testing of a conditional mutant mice provided evidence that actin filament depolymerisation and expression of Cofilin-1 (Cfl1) in the ventral hippocampus may mediate anxiety." (PMID 28381599, 2017). "Thus we argue that dysfunctional cytoskeletal remodeling and the consequent alterations in synaptic plasticity in the hippocampus, and particularly the ventral hippocampus, are the most likely mechanism that contributes to the altered anxiety levels in Cfl1 knockout mice." (PMID 23055942, 2012).
breast tumor (3 papers, 2013 to 2024). "CFL1, on the other hand, binds to actin to depolymerize the actin microfilament, so that it plays a significant role in breast tumour migration and metastasis." (PMID 28903403, 2017). "CFL1 showed the strongest correlation with the metastatic potential of breast tumors." (PMID 39281318, 2024).
esophageal cancer (3 papers, 2021 to 2024). A primary or metastatic malignant neoplasm involving the esophagus. "A previous study reported that autoantibodies against CFL1 and β-actin were useful biomarkers for diagnosing and predicting the prognosis of patients with esophageal carcinoma." (PMID 36875818, 2023). "For example, studies showed that the pathological classification and clinical stage of esophageal cancer was closely related to the expression of CFL1." (PMID 33791303, 2021). "Therefore, the present study aimed to evaluate the serum levels of anti-WDR1 antibodies (s-WDR1-Abs) combined with serum levels of anti-CFL1 antibodies (s-CFL1-Abs) in patients with esophageal carcinoma." (PMID 36875818, 2023). "The combination of positive anti-WDR1 antibodies with negative anti-CFL1 antibodies may be a poor prognostic factor for patients with esophageal carcinoma." (PMID 36875818, 2023). "On the whole, the present study demonstrates that the combination of positive anti-WDR1 antibodies with negative anti-CFL1 antibodies in serum may be a poor prognostic factor for patients with esophageal carcinoma." (PMID 36875818, 2023).
leukemia (3 papers, 2022 to 2025). A malignant (clonal) hematologic disorder, involving hematopoietic stem cells and characterized by the presence of primitive or atypical myeloid or lymphoid cells in the bone marrow and the blood. "The cofilin 1 (CFL1) signaling pathway was shown to be involved in diallyl disulfide (DADS)-induced differentiation and inhibitory effects on the proliferation, migration, and invasion of human leukemia HL-60 cells." (PMID 40868343, 2025). "There were many leukemia-related genes in the up-regulated genes of K1 group, such as UBB (P=1.56e-50), MIF (P=2.76e-50), DRAP1 (P=1.72e-49), RPS25 (P=1.9e-49), EIF3K (P=4.77e-49), SSNA1 (P=1.27e-48), GPX4 (P=3.01e-48), PHB2 (P=7.13e-48), NME2 (P=2.44e-47) or CFL1 (P=4.07e-47)." (PMID 36408189, 2022).
liver disease (3 papers, 2016 to 2023). "We also noticed that accumulation of CFL1 was positively correlated with the progression of liver disease." (PMID 27708241, 2016). "Both of these in vivo and in vitro results have demonstrated that accumulation of CFL1 induced by HBx was highly conserved and specifically related to the occurrence and development of liver disease." (PMID 27708241, 2016). "More importantly, CFL1 is specifically accumulated in HBV-associated HCC (HBV-HCC) liver samples, which expression level is positively correlated with the severity of HBV-related liver disease." (PMID 34531900, 2021). "More importantly, CFL1 and ADFP were specifically accumulated in HBV-associated HCC (HBV-HCC) patient samples, and their expression levels were positively correlated with the severity of HBV-related liver disease." (PMID 27708241, 2016).
liver fibrosis (3 papers, 2023 to 2024). "Cofilin-1 is an actin-binding protein that regulates the cytoskeleton dynamics in hepatic stellate cells (HSCs), triggering the deposition of type I collagen during liver fibrosis." (PMID 39683940, 2024).
pancreatic ductal adenocarcinoma (3 papers, 2018 to 2025). An infiltrating adenocarcinoma that arises from the epithelial cells of the pancreas. "For instance, in pancreatic ductal adenocarcinoma, CFL1 overexpression enhances m6A on seRNA, recruiting MLL1 for H3K4me3 modification." (PMID 39604829, 2024). "Positive UGP2 and CFL1 expression was negatively correlated with the postoperative survival time and positively correlated with the mortality of the patients with pancreatic ductal carcinoma." (PMID 29347944, 2018). "UGP2 and CFL1 were positively expressed in 62 (58.5%) and 56 (52.8%) of the 106 pancreatic ductal carcinoma cases, respectively." (PMID 29347944, 2018). "The UGP2 and CFL1 expression levels were positively correlated in pancreatic ductal carcinoma (P = 0.006)." (PMID 29347944, 2018). "The results of this study showed that the positive expression rates of the UGP2 and CFL1 proteins were significantly higher in pancreatic ductal carcinoma than those in paracancerous tissues and benign lesions (P < 0.05 or P < 0.01)." (PMID 29347944, 2018). "This study investigated UGP2 (uridine diphosphate-glucose pyrophosphorylase-2) and CFL1 (cofilin-1) expression in pancreatic ductal carcinoma (PDC), paracancerous tissue (PT), benign lesions (BL), and normal tissue (NT) and their clinicopathological significance." (PMID 29347944, 2018). "Furthermore, the relationship of the expression levels of UGP2 and CFL1 to the prognosis of patients with pancreatic ductal carcinoma was explored." (PMID 29347944, 2018). "CFL1 is overexpressed in pancreatic ductal adenocarcinoma (PDAC) and facilitates oncogene transcription relying on the CFL1-METTL3-seRNA m6A-YTHDC2/MLL1 axis." (PMID 40483535, 2025).
Papillary thyroid carcinoma (3 papers, 2018 to 2020). "Cofilin-1 is determining the direction of cell migration and has importance for metastasis in papillary thyroid cancer." (PMID 30545079, 2018). "In a PTC (Papillary thyroid carcinoma) lymph node metastasis mouse model, tissue microarray data showed that simultaneous over-expression of protein kinase Aurora-A and CFL-1 (a regulator of actin polymerization) correlated with lymph node metastasis in thyroid cancer tissue." (PMID 31906878, 2020).
schizophrenia (3 papers, 2014 to 2023). A major psychotic disorder characterized by abnormalities in the perception or expression of reality. "Patients with schizophrenia showed significantly lower ADAR2 expressions in both Glyceraldehyde 3-phosphate dehydrogenase (GAPDH)- and CFL1-normalized data (P < 0.05)." (PMID 24443933, 2014).
acute kidney injury (2 papers, 2023 to 2024). Sudden and sustained deterioration of the kidney function characterized by decreased glomerular filtration rate, increased serum creatinine or oliguria. "Moreover, CFL1 triggers ferroptosis by modulating NF-κB signalling or the ER stress pathway to induce acute kidney injury (AKI)." (PMID 39872538, 2024).
acute myelocytic leukemia (2 papers, 2024 to 2025). "We evaluated the expression of CFL1 in patients with chronic myeloid leukemia in the chronic phase (CML-CP), acute myelocytic leukemia (AML) and healthy controls." (PMID 38495482, 2024).
asthma (2 papers, 2011 to 2015). "We also observed an increase in CFL1, which has been implicated as an inhibitor of glucocorticoid function in hormone-resistant HeLa cells and in CD4+ T cells from patients with severe, glucocorticoid-insensitive asthma." (PMID 21388553, 2011). "Particularly differences in the expression of cyclophilin A, cofilin 1 and zinc finger containing CCHC domain protein 11 could be correlated to the function of B lymphocytes as initiators of T lymphocyte independent asthma-like responses." (PMID 26398101, 2015). "The increase in CFL1 expression in the lungs of neonatal rats exposed to EPFR-containing particles suggests that pediatric exposure to EPFR-containing PM is a potential mechanism responsible for the development of severe, glucocorticoid-insensitive asthma in humans." (PMID 21388553, 2011).
astrocytomas (2 papers, 2015 to 2016). "Later, Cfl-1 was identified in different tumor cell lines and tissues including adenocarcinomas, osteosarcoma, lymphoid tissue neoplasms, astrocytoma, glioma, and neuroblastoma." (PMID 28025492, 2016). "Cfl-1 may serve as a predictor of poor response to platinum-based chemotherapy in human ovarian cancer cells and in astrocytomas cells." (PMID 28025492, 2016). "A previous study revealed that cofilin-1 (CFL1) was significantly upregulated in radioresistant astrocytomas, which indicated that CFL1 may be involved in the radioresistant phenotype and therefore may be a target for increasing radiosensitivity." (PMID 25529407, 2015).
bladder (2 papers, 2019 to 2022). "As podocytes recover from injury, they undergo actin cytoskeletal remodelling, a process tightly regulated by cofilin-1, which was previously proposed as a kidney injury biomarker." (PMID 35884827, 2022).
bladder tumor (2 papers, 2017 to 2019). "Human bladder tumor tissue specimens were collected to detect the expression of miR-182-5p and Cofilin 1 by qRT-PCR." (PMID 30858759, 2019). "Present results suggest that miR-182-5p could inhibit human bladder tumor growth by repressing Cofilin 1 expression." (PMID 30858759, 2019). "In addition, Cofilin 1 overexpression increased, while Cofilin 1 knockdown decreased, bladder tumor volumes in mouse xenograft experiments." (PMID 29190896, 2017).
brain ischemia (2 papers, 2018 to 2021). Diminished or absent blood supply to the brain caused by obstruction (thrombosis or embolism) of an artery resulting in neurologic damage. "We first reported that the increase in cofilin-1 was associated with cerebral ischemia-reperfusion in the motor cortex." (PMID 33777942, 2021). "In this study, we aimed to identify the regulatory factors (cofilin-1, Arp2/3, and drebrin-like) of actin cycling/turnover related to cerebral ischemia-reperfusion." (PMID 33777942, 2021). "Cerebral ischemia-reperfusion leads to the motor cortex injury with the cofilin-1 increase in the penumbra and is partially related to dyskinesia, suggesting that cofilin-1 plays an important role during cerebral ischemia-reperfusion." (PMID 33777942, 2021). "Cerebral ischemia-reperfusion activates SSH-1L and CIN, causing active cofilin-1 to emerge and affecting the functions of cofilin-1." (PMID 33777942, 2021). "After cerebral ischemia-reperfusion, a large amount of cofilin-1 accumulates in the cytoplasm, which may enter the nucleus and accelerate the transcription of mRNA (including cofilin-1 mRNA)." (PMID 33777942, 2021).
dermatomyositis (2 papers, 2011 to 2017). Dermatomyositis (DM) is a type of idiopathic inflammatory myopathy characterized by evocative skin lesions and symmetrical proximal muscle weakness. "Anti-cofilin 1 antibodies have been detected in a few patients with rheumatoid arthritis, SLE or polymyositis and/or dermatomyositis." (PMID 21569507, 2011).
dilated cardiomyopathy (2 papers, 2022). Cardiomyopathy which is characterized by dilation and contractile dysfunction of the left and right ventricles. "We previously highlighted that elevated ERK1/2 signaling catalyzes cofilin-1 phosphorylation on T25 and alters actin dynamics in dilated cardiomyopathy caused by mutations in LMNA7." (PMID 36550158, 2022). "Lamin A/C gene mutations cause dilated cardiomyopathy associated with cofilin-1 phosphorylation and actin destabilization." (PMID 36550158, 2022). "Previous studies in models of dilated cardiomyopathy caused by LMNA gene mutations have shown sarcomeric organization defects associated with abnormal activation of the Cofilin 1, ERK1/2, and p38α pathways in the heart." (PMID 33624748, 2022). "In summary, we show for the first time an actin-microtubule cytoskeletal interplay mediated by cofilin-1 and MRTF-A/SRF, promoting the dilated cardiomyopathy caused by LMNA mutations." (PMID 36550158, 2022).
endometriosis (2 papers, 2021 to 2025). The growth of functional endometrial tissue in anatomic sites outside the uterine body. "They observed abnormally high expression of LIMK1 and CFL1, which was closely associated with increased invasiveness and proliferation of eutopic endometrial stromal cells from endometriosis patients compared to those from the endometrium of control group." (PMID 40072086, 2025). "Another protein related to CFL1 in endometriosis is platelet-derived growth factor (PDGF), which induces cell proliferation." (PMID 40072086, 2025). "In eutopic endometrium of endometriosis patients, silencing CFL1 could block PDGF-induced proliferation." (PMID 34076143, 2021).
epithelial dysplasia (2 papers, 2011 to 2018). "In PT and BL with positive UGP2 and CFL1 expression, mild to severe atypical hyperplasia or intraepithelial neoplasia of grades II–III was observed in ductal epithelium." (PMID 29347944, 2018). "Immunohistochemical examination indicated that enhanced expression of PKM2 and cofilin-1 were correlated with the severity of epithelial dysplasia, as well as a relatively poor prognosis." (PMID 22087286, 2011). "Additionally, the ductal epithelia of the paracancerous tissues and benign lesions with positive UGP2 and CFL1 expression showed mild to severe atypical hyperplasia or intraepithelial neoplasia (grades II–III)." (PMID 29347944, 2018). "In paracancerous tissues and benign lesions with positive UGP2 and CFL1 expression, mild to severe atypical hyperplasia or grade II–III intraepithelial neoplasia was observed in the ductal epithelium." (PMID 29347944, 2018).
glioblastoma (2 papers, 2019 to 2020). The most malignant astrocytic tumor (WHO grade IV). "The NKCC1-regulated phosphorylation of cofilin-1 has been revealed in glioblastoma, and we found that inhibiting cofilin-1 phosphorylation with peptide S3 occluded LTP-induced PAP shrinkage, suggesting a shared molecular pathway." (PMID 32976770, 2020). "In glioblastoma cells, NKCC1 provides a protein scaffold regulating the phosphorylation of cofilin-1, and in neurons, transporter KCC2 plays a similar role." (PMID 32976770, 2020). "We demonstrate that RNA isolated from pseudopodia of hGCs contains migration-specific transcripts including Cdc42, Cofilin-1, Ezrin, Ilk, Limk, STAT3, MMP2, and Itgb1, recently described as part of intracellular pathways related to glioblastoma migration." (PMID 30353164, 2019).